CD4 (CD4 molecule)
Diseases named in the same sentence as CD4 in open-access papers (continued):
Sharing a sentence is not in itself a finding about the gene and the disease.
neurological disease (continued). "The HIV-1 RNA detection rate in CSF was higher in patients with neurological diseases, in those with a CD4 count lower than 200 cells/mm3, and in those not receiving antiretroviral therapy, as well as in patients with detectable plasma HIV-1 RNA." (PMID 18096083, 2007). "Previously, we tested whether pseudoviruses carrying 14 Envs derived from five subjects with neurological disease infected cells expressing CCR5 but not CD4." (PMID 30415390, 2019). "Additionally, since GZMK can be employed by CD4+ and CD8+ T cells along with γδ T cells, a summative effect of multiple cell types producing this enzyme could differentially influence neuroinflammation in various neurologic diseases." (PMID 39744938, 2025). "EBNA-1-specific CD4 T cells and CD4 T cells recognizing EBV-infected B lymphoblastoid cell lines have been detected in the CSF of patients with MS and patients with other inflammatory and non-inflammatory neurologic diseases." (PMID 34305896, 2021).
adenocarcinoma (51 papers, 2007 to 2026). A common cancer characterized by the presence of malignant glandular cells. "For adenocarcinoma patients, memory B‐cell and resting CD4+ T-cell fractions were associated with better OS, whereas the neutrophil, follicular helper cell, M0 macrophage, and M2 macrophage fractions were associated with a shorter OS." (PMID 36793597, 2023). "Representative figures of immunohistochemistry in adenocarcinoma show that high YTHDF1 or YTHDF2 cases are associated with low CD4, CD8 and high FOXP3 expression in both PD-1 inhibitor treatment and non-treatment groups." (PMID 36479088, 2022). "For adenocarcinoma patients, higher CD4+/CD8+ T cell ratios and lower CD8+ T cell levels predicted better efficacy (P = 0.0155, P = 0.0119)." (PMID 39483483, 2024). "In the adenocarcinoma group receiving PD-1/PD-L1 inhibitor treatment, the immunohistochemical expression of YTHDF1 was significantly negatively associated with CD4 expression." (PMID 36479088, 2022). "The YTHDF1 or YTHDF2 mRNA expression was significantly negatively associated with CD4, CD8, and FOXP3 mRNA expression in adenocarcinoma." (PMID 36479088, 2022). "When calculating the relative frequency of each Th subset, expressed as percentage of all CD3+CD8- Th cells, Treg cells and Th2 cells were found to each represent approximately 20-25% of all CD4+ T cells, both in adenocarcinoma and SCC." (PMID 34868011, 2021). "It was noted that there was a statistically significant difference for inflammation between the control and study group with the adenocarcinoma subtype and for intratumoral CD4/CD8 ratio between the control and study group with SCC subtype (respectively, p = 0.0008 ve p = 0.0139)." (PMID 38468248, 2024). "Additionally, HT29 had a significantly lower capacity to induce IL-10 production by CD4+CD25+ lymphocytes than the HeLa adenocarcinoma cell line." (PMID 36194602, 2022). "Interestingly, the PD-L1 expression on adenocarcinomas-conditioned moDCs positively correlated with the phagocyte activity, IL-6 production, and IL-10 producing CD4+CD25+ T cell activation." (PMID 36194602, 2022). "HIV infection and CD4 count were not clearly associated with SCC or adenocarcinoma in our entire study population." (PMID 21702999, 2011). "Early responders exhibited robust CD4+ and CD8+ T cell presence throughout adenocarcinoma regions and adjacent pancreatic tissue." (PMID 41041061, 2025). "When compared to normal and FAP mucosa, we find two critical determinants of disease prognosis, such as CD4+:CD8+ T cell ratio and M1:M2 macrophage ratio decrease in FAP polyp and adenocarcinoma/sporadic CRC samples." (PMID 39605357, 2024). "Stromal CD4 TILs were identified as a significant marker for predicting the PFS after pembrolizumab therapy, especially in patients with non-adenocarcinoma and high PD-L1 expression." (PMID 36662367, 2023). "In adenocarcinoma, YTHDF2 was negatively correlated with CD4 and CD8 and positively correlated with FOXP3 in protein and mRNA analysis." (PMID 36479088, 2022). "PCa samples presented similar patterns for CD3+, CD4+, and CD8 lymphocytes that formed clusters adjacent to adenocarcinoma areas, which appeared separated from the lymphocytic infiltration." (PMID 35884977, 2022). "When expressed as percentage of all CD4+ T cells, Th2 was the most frequent Th subset in TLS in both adenocarcinoma and SCC." (PMID 34868011, 2021). "Wenner et al29 reported that Doc induced an increase in both CD4+ and CD8+ TILs over saline treatment in transgenic adenocarcinoma of the mouse prostate‐C2‐bearing mice." (PMID 31018021, 2019). "In the transgenic adenocarcinoma of mouse prostate (TRAMP) model, activated effector CD4+ T cells have been reported to release active TGFβ1." (PMID 30832732, 2019). "Specifically, activated CD4+T cells, regulatory T cells (Tregs), natural killer T cells, central memory CD8+T cells, and M1 macrophages exhibited elevated infiltration in the solid pattern adenocarcinomas." (PMID 38505588, 2024).
adenocarcinoma (continued). "Recently, a new mouse model of CAC genetically engineered mice to express the dominant negative TGFβ receptor II in CD4 and CD8 T cells (CD4-dnTGFβRII/AOM), and after challenge with a single dose of AOM, they formed macroscopically invisible flat adenocarcinoma lesions." (PMID 37884500, 2023). "BPH tissue samples presented CD3+, CD4+, and CD8 lymphocytes with their distribution, such as healthy tissue, but they sometimes may form significantly smaller clusters than those of the adenocarcinoma tissue." (PMID 35884977, 2022). "Similarly, patients progressed to adenocarcinoma displayed increased CD20+ (p < 0.001), CD4+ (p = 0.003) and CD8+ (p = 0.014) lymphocytes in the background non-dysplastic BO compared with non-progressors." (PMID 31831860, 2020). "The levels of dendritic cells (R = 0.61), macrophages (R = 0.56), neutrophils (R = 0.55), CD8+ (R = 0.32), and CD4+ (R = 0.31) T cells, as well as B cells (R = 0.10) infiltration, were positively correlated (p < 0.05) with the expression of ADGRF5 in the rectum of patients with adenocarcinoma." (PMID 36497132, 2022). "However, the negative correlation of the expression of APE1 and CD4+ native T cells was only observed in the adenocarcinoma subset." (PMID 33676448, 2021). "There was no clear association between CD4 count and SCC or adenocarcinoma." (PMID 21702999, 2011).
neurodegenerative disease (50 papers, 2009 to 2026). A disorder of the central nervous system characterized by gradual and progressive loss of neural tissue and neurologic function. "Neurodegenerative diseases are often accompanied with neuroinflammatory process in which large numbers of DCs and CD4 T cells are recruited into the CNS and cause irreversible neural impairment." (PMID 19924241, 2009). "In the central nervous system (CNS), it has been suggested that CD4+ T cells facilitate neurodegenerative disease pathology through interaction with microglia." (PMID 38317227, 2024). "Our results are in line with the literature documenting the interaction between reactive Cx3cr1+ cells and CD4+ T cells in various neurodegenerative disease models." (PMID 37689689, 2023). "In recent years, different studies considered the mechanism of altered regulation of CD4+ T-cell activity in neurodegenerative diseases." (PMID 36361799, 2022). "The model can perturb immune signaling and metabolism within a CD4+ T cell and obtain clinically relevant outcomes that help identify novel drug targets for infectious, autoimmune, metabolic, and neurodegenerative diseases." (PMID 36418318, 2022). "The effect of drugs on the Interaction between microglia and CD4+ T cells infiltrating the brain during neurodegenerative diseases is another one." (PMID 33085226, 2020). "CD4+ Th2 cells mainly exhibit neuroprotective properties in the context of neurodegenerative diseases." (PMID 33408628, 2020). "With regards to other neurodegenerative diseases, circulating lymphocytes have also been found to be decreased in PD patients, mainly of the “naive” helper T-cell phenotype (CD4+CD45RA+)." (PMID 32733370, 2020). "In the next sections, we will describe the influence of oxidative stress in some of the most common neurodegenerative diseases, and the subpopulations of CD4+T cells are predominant under those conditions." (PMID 29755324, 2018). "These kinds of cells play a crucial role in the progression of neurodegenerative diseases; however, the intensity and type of CD4+T response vary between pathologies." (PMID 29755324, 2018). "It is accepted that MS is an inflammatory and neurodegenerative disease primarily driven by myelin-reactive CD4+ T helper 1 (Th1) cells, CD4+ T helper 17 (Th17) cells, CD8+ T cells, and B cells that target and damage the myelin sheath." (PMID 29915595, 2018). "Growing evidence has indicated a fundamental role of CD4+ T-cells in the regulation of neuroinflammation and consequent neurodegeneration in a number of neurodegenerative diseases." (PMID 25441979, 2014). "Dysfunction of FoxP3+CD25+CD4+ Tregs was observed in the early stages of several neurodegenerative diseases." (PMID 23983771, 2013). "Circulating CD4+ T cells are required for controlling the local detrimental inflammation in neurodegenerative diseases, and for supporting neuronal survival, including that of MN." (PMID 21829620, 2011). "Different subsets of CD4+ T cells, such as Th1, Th2, Th17, and regulatory T cells, can differentiate into various cell types and perform distinct roles within the neuroinflammatory environment of neurodegenerative diseases." (PMID 40536931, 2026). "Nevertheless, extending the use of CAR molecules to CD4+ T cells designed to promote CNS repair could represent a substantial breakthrough in cellular immunotherapy for neurodegenerative diseases." (PMID 38600001, 2024). "CD4+ Th1 infiltration in the brain is seen in various neurodegenerative diseases." (PMID 33408628, 2020). "Furthermore, we will describe the role that specific CD4+T cell subpopulations play in some of the most important neurodegenerative diseases." (PMID 29755324, 2018). "The aim of this work is to review the effect of the state of oxidative stress on the loss of regulation of the inflammatory response on the microglia and astrocytes, the induction of different CD4+T cell populations in neuroinflammation, as well as its role in some neurodegenerative diseases." (PMID 29755324, 2018).
neurodegenerative disease (continued). "Inflammatory CD4+ T cells, including type 1 helper T (Th1), Th17, GM-CSF-producing CD4+ T cells, and γδ T cells, may recognize central nervous system (CNS) antigens and contribute to neuroinflammation and the progression of neurodegenerative diseases." (PMID 36180897, 2022). "Specific transcriptomic signatures associated with CD4 and CD8 memory T cell compartments have been described in several other pathologies, including autoimmunity, but here we report these types of signatures associated with memory T cells in neurodegenerative disease." (PMID 35314697, 2022). "The importance of FoxP3+CD25+CD4+ Tregs in regulating and maintaining homeostasis between both the immune system and the brain is demonstrated by their roles in CNS diseases, especially neurodegenerative diseases, such as MS, Parkinson's disease (PD) and Alzheimer's disease (AD)." (PMID 23983771, 2013). "The CD4+ cells were selected for analysis, as microglia express MHC-II during neurodegenerative diseases." (PMID 40842561, 2025). "Studies have pointed out that inhibition of OPA1 enhances the progression of neurodegenerative diseases, and OPA-1 regulates apoptosis resistance of OXPHOS IL-17-producing CD4 T cells by regulating mitochondrial fusion and limiting mitophagy." (PMID 37434203, 2023). "It is the causative infectious agent of several diseases including an aggressive CD4+ T-cell malignancy (ATL) and a progressive neurodegenerative disease (HAM/TSP)." (PMID 35602078, 2022). "In addition, both CD4+ and CD8+ T cells of PD patients expressing higher levels of inflammatory cytokines also expressed higher levels of LRRK2 suggesting that LRRK2 protein expression is associated with the inflammatory response characteristically seen in this neurodegenerative disease." (PMID 28649611, 2017). "Beyond the large body of literature connecting aberrant microglial IFN signaling in neurodegenerative disease, additional evidence points to important roles for endothelial cells, the choroid plexus, and IFN-responsive CD4 and CD8 T cells in neurodegenerative disease." (PMID 39421070, 2024). "Nevertheless, the alteration of CD4+ and CD8+ T cells observed in the periphery in neurodegenerative diseases indicates that there is persistent antigenic challenge and T cells are playing a role in neurodegenerative diseases." (PMID 23724961, 2013). "Finally, having shown the most promise in neurodegenerative diseases, introducing these TCR molecules to a pre-stratified autologous CD4+ T cell population could ensure both minimal cytotoxicity and a lack of rejection or induction of graft-versus-host disease." (PMID 38600001, 2024). "These are novel findings that point towards a diminished role for CD4+ T cells in SPMS and add further evidence for SPMS being a neurodegenerative disease stage, not an inflammation-driven one." (PMID 27570566, 2016).
psychiatric disorder (42 papers, 2011 to 2026). A disorder characterized by behavioral and/or psychological abnormalities, often accompanied by physical symptoms. "Chemsex should be routinely screened and addressed in clinical practice, particularly for people with mental illness and low CD4 cell counts, who are at higher risk for severe intoxications." (PMID 35180855, 2022). "PLWH naïve to ART, with higher CD4 + T count and with psychiatric disorders were more likely to develop a CNS-AE." (PMID 35632768, 2022). "D2R‐specific T cells in paediatric patients with movement and psychiatric disorders (n = 24) were identified by determining CD4+ T‐cell activation when whole blood was stimulated with 10 master pools of human D2R peptides." (PMID 33425355, 2020). "The associations between history of mental illness and mortality were marginally attenuated in a multivariable model adjusted for age, sex, year of ART initiation, treatment programme, and CD4 cell count and WHO clinical stage at ART initiation (model 2)." (PMID 32971055, 2020). "A border-line significance was observed for HAART therapy, higher cholesterol levels, lower Nadir CD4 T-cell counts, presence of psychiatric disorders." (PMID 23349927, 2013). "In contrast, in the non-DTG cohort, PLWH with higher CD4 + T counts and those with baseline psychiatric disorders were more at risk of CNS-AEs." (PMID 35632768, 2022). "For the identification test, a history of psychiatric disorder not otherwise specified and CD4 nadir lymphocyte count was associated with cognitive performance after taking into account the baseline, assessment, and treatment effects." (PMID 30298202, 2019). "We hypothesized that mental illness symptoms and unhealthy substance use would be associated with non‐nucleoside reverse transcriptase inhibitor (NNRTI)‐based ART (still commonly used in LMICs), lower CD4 count, detectable viral load, comorbid NCDs and coinfections in our cohort." (PMID 40045453, 2025). "After adjusting for psychiatric disorder not otherwise specified and CD4 nadir lymphocyte count, the effect of treatment on neurocognition was similar (p value = 0.234 vs. p value = 0.178)." (PMID 30298202, 2019). "For the identification test, the covariates psychiatric disorder not otherwise specified and CD4 nadir lymphocyte cell counts were found to be significant at the alpha level of 0.1 and remained in the model after baseline, treatment and visit were added." (PMID 30298202, 2019). "However, the presence of a mental illness diagnosis had a weak negative relationship with CD4 counts (r = −0.279, p = 0.038)." (PMID 35955095, 2022). "Also, the probability of AE reversibility was not different based on sex, ethnicity, CD4 + T-cell count, or CDC stage, nor on people with or without a previous diagnosis of a psychiatric disorder, while older PLWH were those less likely to resolve the CNS-AE in this cohort (p= 0.017)." (PMID 35632768, 2022).